AKAP9 (A-kinase anchoring protein 9)
Diseases named in the same sentence as AKAP9 in open-access papers (continued):
Sharing a sentence is not in itself a finding about the gene and the disease.
gastric cancer (4 papers, 2022 to 2024). A primary or metastatic malignant neoplasm involving the stomach. "Among them, A-kinase anchoring protein 9 (AKAP9) is the most mutated one with recurrent mutation in 14.9% of gastric cancers." (PMID 36317124, 2022). "Consistently, another study showed that somatic frameshift mutations in AKAP9 were occurred in 11.7% of gastric cancer and 17.7% colorectal cancers (CRC) with high microsatellite instability." (PMID 36317124, 2022). "Of note, genetic alterations including depletion and amplification frameshift mutations of AKAP9 have been observed in 10–15% of gastric cancer patients." (PMID 36317124, 2022). "To examine whether AKAP9 expression is associated with patient's prognosis, we analyzed the transcriptomic data of gastric cancers in NCBI GEO Database by Kaplan–Meier Plotter." (PMID 36317124, 2022). "Notably, genetic alterations of AKAP9 are more complicated in gastric cancer, including depletion, amplification, and frameshift mutations." (PMID 36317124, 2022). "Although AKAP9 is frequently mutated or amplified, its expression in gastric cancer remains unknown." (PMID 36317124, 2022). "So far, the pro-cancerous activity of AKAP9 has been extensively studied in colorectal cancer, gastric cancer, and acute myeloid leukaemia, where its action was related to cancer cell proliferation, migration, and invasion, as well as lower survival." (PMID 38203733, 2024). "To understand the role of AKAP9 in gastric cancer, we knocked down AKAP9 by infecting NCI-N87 gastric cancer cells with a mixture of two shRNAs targeting AKAP9 or shGFP lentivirus (as a negative control)." (PMID 36317124, 2022). "No recurrent MET fusions were identified, some of the fusion partners included HLA-DRB1-MET (lung cancer), CD47 (lung cancer), CAPZA2 (gastric cancer), AKAP9 (hepatobiliary cancer), CLIP2 (hepatobiliary cancer), and SLC25A19 (ovarian cancer)." (PMID 36369474, 2022). "We investigated the role of AKAP9 in gastric cancer by performing cell proliferation assay, transwell assay, and mouse xenograft assay." (PMID 36317124, 2022). "In the current study, we found that AKAP9 is overexpressed in gastric cancer and enhances gastric tumorigenesis and metastasis." (PMID 36317124, 2022). "Genetic studies identified a dozen of frequently mutated genes in gastric cancer, such as cadherin 1 (CDH1) and A-kinase anchoring protein 9 (AKAP9)." (PMID 36317124, 2022). "Here, we will explore the role of AKAP9 and its crosstalk with E-cadherin in gastric cancer progression." (PMID 36317124, 2022). "Having demonstrated that AKAP9 is upregulated in gastric cancer patients, we next examine if overexpression of AKAP9 has effects on gastric cancer cell proliferation and migration." (PMID 36317124, 2022). "In conclusion, our study demonstrates that AKAP9 is overexpressed in gastric cancer and functions as an oncoprotein to promote gastric cancer cell proliferation, migration, and tumor growth." (PMID 36317124, 2022). "Our study demonstrates that AKAP9 functions as an oncoprotein to promote gastric cancer cell proliferation, migration, and tumor growth." (PMID 36317124, 2022). "AKAP9 can act as an oncoprotein to promote the progression of gastric cancer." (PMID 39317949, 2024). "Notably, gastric cancer patients with high AKAP9 expression have shorter survival time than patients with low AKAP9 expression." (PMID 36317124, 2022). "Moreover, we reveal a possible molecular link showing that AKAP9 is a critical effector downstream of CDH1 in gastric cancer." (PMID 36317124, 2022). "Using qRT-PCR, we analyzed the mRNA levels of AKAP9 in gastric cancer patient samples." (PMID 36317124, 2022). "This study is aimed to characterize the expression and function of AKAP9 in gastric cancer." (PMID 36317124, 2022).
gastric cancer (continued). "In contrast to the results of AKAP9 knockdown, AKAP9 overexpression significantly enhanced cell proliferation and cell migration, indicating that upregulation of AKAP9 may play a critical role in gastric cancer growth and metastasis." (PMID 36317124, 2022). "However, it is unknown of the expression and role of AKAP9 in gastric cancer." (PMID 36317124, 2022). "Given that both AKAP9 and CDH1 are frequently altered in gastric cancer and play a vital role in controlling gastric cancer cell migration, we next examine the correlation between these two functional-relevant events." (PMID 36317124, 2022). "We also identify CDH1 as a potential negative regulator of AKAP9 expression, through which CDH1 regulates gastric cancer migration and invasion." (PMID 36317124, 2022). "However, it is unknown what is the function of AKAP9 in gastric cancer." (PMID 36317124, 2022).
cardiac arrhythmia (3 papers, 2015 to 2021). Any disturbances of the normal rhythmic beating of the heart or MYOCARDIAL CONTRACTION. "Individual III-4, who died suddenly despite a normal cardiac function, carried LPVs in the AKAP9 and SCN10A genes, both implicated in cardiac arrhythmias." (PMID 34790974, 2021). "The family member had PVs and LPVs in 7 genes implicated in hereditary cardiomyopathies and/or cardiac arrhythmias, including LPVs in SCN10A and AKAP9, which are implicated in cardiac arrhythmias." (PMID 34790974, 2021).
long QT syndrome type 1 (3 papers, 2021 to 2025). "Mutations in Q1 or AKAP9 that abolish their functional interaction result in long QT syndrome type 1 and 11, respectively, which increases the risk of sudden cardiac death during exercise." (PMID 37650513, 2023). "AKAP9 encodes for A-kinase anchoring protein 9, a signaling protein that binds to the regulatory subunit of protein kinase A and has been implicated also as a genetic modifier of congenital long-QT syndrome type 1." (PMID 34177625, 2021). "Conversely, AKAP9’s binding to PP1 leads to the dephosphorylation of KCNQ1, and mutations within this complex have been implicated in type 1 long QT syndrome (LQT1), a potentially fatal inherited arrhythmia syndrome." (PMID 40599813, 2025).
melanoma (3 papers, 2010 to 2021). A malignant, usually aggressive tumor composed of atypical, neoplastic melanocytes. "Intriguingly, patients with primary melanoma or higher tumor stage had significantly worse outcomes, which suggested that AKAP9, VPS13C, ACSL4, and HMOX2 might play a vital role in the overall survival of SKCM through mediating cancer growth and metastasis." (PMID 33663112, 2021). "Functional assays on a subset of these candidates, including MET, ASPM, AKAP9, IMP3, PRKCA, RPA3, and SCAP2, validated their pro-invasion activities in human melanoma cells." (PMID 20520718, 2010). "While investigating the association between expression of hub OS genes and SKCM clinical features, we discovered that patients with metastatic melanoma had significantly increased expression of AKAP9, VPS13C, and ACSL4, while HMOX2 demonstrated higher expression in patients with primary melanoma." (PMID 33663112, 2021). "To this end, we selected 6 genes from the candidate list (ASPM, AKAP9, IMP3, PRKCA, RPA3, and SKAP2) based on literature support (see Discussion) to determine whether their knockdown would impact on the invasion of a human melanoma cell, 1205LU." (PMID 20520718, 2010).
dementia (2 papers, 2021 to 2025). Loss of intellectual abilities interfering with an individual's social and occupational functions. "The ATP‐binding cassette subfamily A member 7 (ABCA7) gene, linked to dementia in African Americans, and unique genetic variants like those in A‐kinase anchor protein 9 (AKAP9) and cytidine deaminase (CDA) genes, emerge as potential contributors." (PMID 40289851, 2025). "Across the most frequent ADSP+ contributors to pathway enrichment, AKAP9 is the only gene absent from the familial dementia and AD GWAS gene sets." (PMID 35005195, 2021).
Romano-Ward syndrome (2 papers, 2023 to 2025). "For targeting SNPs in the human genome, we considered two common SNPs in the Indian population, rs2073874 (ADAMTSL2, C>T) and rs138739292 (AKAP9, G>A), which are linked to Geleophysic dysplasia 1 and Romano-Ward syndrome, respectively." (PMID 36752591, 2023).
Ventricular arrhythmia (2 papers, 2022 to 2024). "This study provides insight into the mechanism underlying cardiac arrest and confirms that AKAP9 loss-of-function variants predispose to serious, life-threatening ventricular arrhythmias." (PMID 36421840, 2022).
acute myeloid leukaemia (1 paper, 2024). "The studies published thus far also show upregulation of AKAP9 gene expression in gastric and CRC cancers, as well as in acute myeloid leukaemia." (PMID 38203733, 2024).
autism (1 paper, 2023). Persistent deficits in social interaction and communication and interaction as well as a markedly restricted repertoire of activity and interest as well as repetitive patterns of behavior. "Some findings reported proteins encoded by AKAP9, another significant gene in the allelic association study, to be highly expressed in autism subjects." (PMID 36817779, 2023).
chronic heart failure (1 paper, 2021). "Changes in the AKAP9 protein expression and its mutations have been associated with the development of systemic diseases, including chronic heart failure (amino acid substitution Ser1570Lys), various types of cancer, and immune system disorders." (PMID 34679534, 2021).
clear-cell renal cell carcinoma (1 paper, 2020). "Like Akap9, Gnb1 is also implicated in kidney disease, where downregulation of the gene is associated with worsened prognosis of clear-cell renal cell carcinoma, as well as in resistance to tyrosine kinase inhibitor drugs in human models of kidney cancer." (PMID 32998684, 2020).
crescentic glomerulonephritis (1 paper, 2015). A histopathologic term for a pattern of diseases characterized by extensive crescent formation in the glomeruli; patients present clinically with rapid deterioration of renal function, and possible progression to end-stage renal failure within weeks or months. "To examine the role of AKAP9 in T effector cell functions in vivo, we used a model of crescentic glomerulonephritis (GN) where mice were pre-immunized with CFA/IgG and then administered an antibody against the GBM." (PMID 26680259, 2015).
gastric tumors (1 paper, 2022). "The qRT-PCR results showed that the mRNA levels of AKAP-9 in gastric tumors were higher than adjacent normal tissues in 25 of 31 matched tissue samples." (PMID 36317124, 2022). "We collected 31 gastric tumors and the matched adjacent normal tissues and examined AKAP9 mRNA levels." (PMID 36317124, 2022). "Overexpression of AKAP9 promoted cell proliferation, migration, and gastric tumor growth." (PMID 36317124, 2022).
glioblastoma (1 paper, 2018). The most malignant astrocytic tumor (WHO grade IV). "Three of these Fyn-induced PKA interactors, AKAP9, PDE4DIP, and CDK5RAP2, were validated biochemically and were shown to exist in complex with Fyn and PKA in a glioblastoma cell line." (PMID 30274258, 2018).
glioma (1 paper, 2025). A benign or malignant brain and spinal cord tumor that arises from glial cells (astrocytes, oligodendrocytes, ependymal cells). "Chronologically, the C1 AKAP9+ glioma cell subpopulation appears to represent the early stage of tumorigenesis." (PMID 39975552, 2025). "Based on inferred copy number variations (CNV), cells with elevated CNV levels were classified as glioma cells revealing three subpopulations: C0 MALAT1+ glioma cells, C1 AKAP9+ glioma cells, and C2 NUSAP1+ glioma cells." (PMID 39975552, 2025). "In contrast, the AKAP9+ Glioma subset in the C1 group was notably involved in the NCAM and VEGF signaling pathways." (PMID 39975552, 2025). "Additionally, we found that the NCAM signaling pathway, involved in cell adhesion, and the VEGF pathway, associated with angiogenesis, were particularly prominent in the C1 AKAP9+ Glioma subpopulation." (PMID 39975552, 2025). "In state 2, C1 AKAP9-expressing glioma cells dominated, while in state 3, C2 NUSAP1-expressing glioma cells were the most abundant." (PMID 39975552, 2025). "Notably, we identified three major glioma cell subpopulations (C0 MALAT1+, C1 AKAP9+, and C2 NUSAP1+), which were highly correlated with tumor malignancy." (PMID 39975552, 2025).
hypertrophic cardiomyopathy (1 paper, 2015). A condition in which the myocardium is hypertrophied without an obvious cause. "We postulate that the novel MVI-AKAP9 interaction could also be important in cardiac muscle since, on one hand, AKAP9 was shown to play a crucial role in the proper functioning of the heart and, on the other hand, mutated MVI was shown to be associated with hypertrophic cardiomyopathy." (PMID 25961040, 2015).
nevus (1 paper, 2021). Nevus (or naevus, plural nevi or naevi, from nævus, Latin for "birthmark") is the medical term for sharply circumscribed[1] and chronic lesions of the skin or mucosa. "NIPBL, AKAP9, and EP400 were mutated in both the nevus and atypical tumor, although the specific mutations were different between the two lesions." (PMID 35052351, 2021).
Obesity (1 paper, 2024). Accumulation of substantial excess body fat. "Among these genes, AHI1, AKAP9, ANKRD12, CCDC18, IFT74, NEXN, etc., have been shown to play an important role in adipose deposition or obesity." (PMID 38474122, 2024).
oral cancer (1 paper, 2022).
renal cell carcinoma (1 paper, 2018). "Interestingly, in line with the findings in our study, somatic mutations in AKAP8 and AKAP9 were found in multiple metastases in a patient with renal cell carcinoma but were both absent in the primary tumor." (PMID 29433456, 2018).
schizophrenia (1 paper, 2015). A major psychotic disorder characterized by abnormalities in the perception or expression of reality. "A recent study found a statistically significant excess of rare missense variants of NRXN1 (MIM 600565) and extremely rare damaging risk variants of AKAP9 (MIM 604001) in schizophrenia patients in Northwest Spain." (PMID 26114114, 2015).
thyroid (1 paper, 2024). "Our analyses based on benign and malignant thyroid lesion tissues have revealed a significant difference in the expression of the AKAP9 gene between healthy and cancerous thyroid tissue." (PMID 38203733, 2024). "Significantly increased expression of AKAP9 in pathologically changed thyroid tissue and in more advanced cancer stages (pT2-4, Stage II-IV) may be potentially used as a thyroid tumorigenesis marker." (PMID 38203733, 2024).
cancer (22 papers, 2016 to 2025). A tumor composed of atypical neoplastic, often pleomorphic cells that invade other tissues. "The one ATA high-risk cancer identified in the cohort was found in a nodule harboring an AKAP9–BRAF fusion, and histologically this was found to be a tall cell variant PTC with nodal disease and ETE." (PMID 40075589, 2025). "In the course of CRC, MALAT1 stimulates the proliferation, invasion, and migration of cancer cells through PRKA kinase anchor protein 9 (AKAP-9), which is associated with cancer progression and metastasis." (PMID 38674413, 2024). "Various genetic alterations of the AKAP9 are known to be primarily associated with cancers of the colorectum, stomach, lungs, and breast." (PMID 38203733, 2024). "Approximately 10 to 18% of samples carrying the mutated AKAP9 gene are reported, depending on the type of mutation and type of cancer." (PMID 38203733, 2024). "Previous research has shown that increased expression of the AKAP9 gene is associated with the proliferation, migration, and invasion of cancer cells, and therefore cancer progression and tumour metastasis." (PMID 38203733, 2024). "Somatic mutations of Akap9 are frequent in many cancers, especially in gastrointestinal malignancies." (PMID 33302499, 2020). "The next and new exciting target in cancer development and progression studies seems to be A-kinase anchoring protein 9 (AKAP9)." (PMID 38203733, 2024). "Our studies on tissues from patients with benign and malignant thyroid lesions showed a significant contribution of the BRAF V600E mutation and changes in the expression of RASSF1A, DIRAS3, and AKAP9 genes in developing this type of cancer." (PMID 38203733, 2024). "At the same time, as in other types of cancer, later AKAP9 expression alterations promote tumour development and invasiveness of tumour cells." (PMID 38203733, 2024). "Among these proteins, AKAP4 and AKAP9 have been extensively studied as cancer-promoting factors, whereas AKAP12 and recently AKAP13 have been shown to play the opposite role, although their mechanism of action has not been studied in depth." (PMID 36203781, 2022). "Results indicated that the four hub genes were all significantly related to metastasis (P < .05); AKAP9, VPS13C, and ACSL4 were positively associated with metastatic ability, while HMOX2 was negatively associated with cancer metastasis." (PMID 33663112, 2021). "Among them, AKAP4 and AKAP9 have been widely studied as cancer-promoting factors, while AKAP12 have proved to play the opposite role." (PMID 34722307, 2021). "Within these genes, AKAP9, CENPE, PRKCI, RDX, RECQL, and USO1 have also been reported to be associated with cancer progression." (PMID 31426369, 2019). "Because of the previously reported implication of AKAP9 in breast- and other cancers, the analysis was extended to include all members of the AKAP gene family." (PMID 29433456, 2018). "Four genes (AKAP9, ATM, CREBBP, and NF1) were mutated in only one subject but were reported on the Cancer Gene Census list, and the mutations were predicted to be detrimental by SIFT." (PMID 27689332, 2016). "The way AKAP9 acts in cancers still needs to be better understood." (PMID 38203733, 2024). "Within this subclone that may have emerged in response to treatment, mutations were also detected within the genes AKAP9 and ACSL6, both of which are listed in the COSMIC cancer gene census." (PMID 37081523, 2023). "AKAP9 has been reported to be involved in the development or metastasis of several cancers." (PMID 35055428, 2022). "A-kinase anchoring protein 9 (AKAP9) is a target gene for the cancer-promoting effect of MALAT1." (PMID 34820188, 2021). "While investigating the list of recurrently mutated cancer genes we found that AKAP9 carried an unexpected number of both silent and nonsilent mutations in the metastatic lesions." (PMID 29433456, 2018).
cancer (continued). "Previous studies have shown that MALAT1 enhances AKAP-9 expression in CRC cells in vitro, functionally promoting cancer cell proliferation, invasion, migration, and metastatic spread." (PMID 39471147, 2024). "Therefore, we further investigated connections between AKAP9, VPS13C, ACSL4, and HMOX2 expression and cancer metastasis." (PMID 33663112, 2021).